DEF6 (DEF6 guanine nucleotide exchange factor)
Description:
Phosphatidylinositol 3,4,5-trisphosphate-dependent guanine nucleotide exchange factor (GEF) which plays a role in the activation of Rho GTPases RAC1, RhoA and CDC42. Can regulate cell morphology in cooperation with activated RAC1 (By similarity). Involved in immune homeostasis by ensuring proper trafficking and availability of T-cell regulator CTLA-4 at T-cell surface. Plays a role in Th2 (T helper cells) development and/or activation, perhaps by interfering with ZAP70 signaling (By similarity).
Synonyms: IBP; SLAT; SWAP70L; IMD87
Tractability: Antibody: UniProt places it where antibodies can reach, with high confidence; its Gene Ontology location is reachable by antibodies, with medium confidence. PROTAC: ubiquitination databases record sites on it; its protein half-life has been measured.
Gene: Protein-coding gene on chromosome 6 (35,297,818 to 35,321,909, forward strand). Ensembl gene ENSG00000023892.
Subcellular location: Cytoplasm; Cell membrane; Nucleus; Cytoplasm, cytoskeleton; Cytoplasm, perinuclear region; Cell projection, filopodium
Subcellular location (Human Protein Atlas): Nucleoplasm
Pathways (Reactome):
Signal Transduction: CDC42 GTPase cycle; RAC1 GTPase cycle; RAC2 GTPase cycle; RHOA GTPase cycle
Gene Ontology:
Molecular function: protein binding; guanyl-nucleotide exchange factor activity
Biological process: vesicle-mediated transport to the plasma membrane; regulation of small GTPase mediated signal transduction
Cellular component: cytoplasm; membrane; nucleoplasm; nucleus; plasma membrane; cytosol; cytoskeleton; filopodium; perinuclear region of cytoplasm
Genetic constraint (gnomAD): Loss-of-function variants: 33 observed, 72.38 expected, observed/expected ratio (o/e) 0.46, 90% interval 0.34 to 0.61. The upper end of that interval is the gene's LOEUF score, 0.61, which puts it in group 2 of 6, group 1 being the genes least tolerant of losing a copy. Missense variants: 559 observed, 775.75 expected, observed/expected ratio (o/e) 0.72, 90% interval 0.67 to 0.77. Synonymous variants: 294 observed, 318.09 expected, observed/expected ratio (o/e) 0.92, 90% interval 0.84 to 1.02.
Gene-disease validity (ClinGen):
ClinGen rates the evidence that DEF6 causes each of these diseases.
immunodeficiency 87 and autoimmunity (autosomal recessive): Moderate. An autosomal recessive immunologic disorder with wide phenotypic variation and severity.
Homologues: Orthologues: chimpanzee DEF6 (99% identical), macaque DEF6 (99% identical), rabbit DEF6 (95% identical), pig DEF6 (94% identical), rat Def6 (93% identical), mouse Def6 (92% identical), dog DEF6 (87% identical), guinea pig DEF6 (77% identical), zebrafish def6a (65% identical), tropical clawed frog def6 (60% identical), zebrafish def6b (36% identical), Caenorhabditis elegans F31D4.5 (13% identical). Paralogues in human: SWAP70 (43% identical), PLEKHD1 (17% identical).
Diseases named in the same sentence as DEF6 in open-access papers:
DEF6 is named in the same sentence as 51 diseases in open-access papers, as found by Europe PMC text mining. Sharing a sentence is not in itself a finding about the gene and the disease. The quoted sentences say what the papers report.
Autoimmunity (10 papers, 2012 to 2026). The occurrence of an immune reaction against the organism's own cells or tissues. "In studies on murine autoimmunity, DEF6 deficiency has shown variable effects depending on the genetic background and the specific model of autoimmune disease." (PMID 41294018, 2025). "DEF6 is a gene associated with the immune system and is thought to play a crucial role in autoimmunity." (PMID 36686789, 2022). "Given the marked response of P1 to Abatacept (CTLA-4-Ig) treatment enabling clinical disease remission, we hypothesized that autoimmunity in DEF6 deficiency may be linked to aberrant CTLA-4 regulation." (PMID 31308374, 2019). "Increased effector T-cell counts, lymphocytic organ infiltration, as well as multiple types of autoimmunity are commonly observed in patients with CTLA-4 insufficiency, LRBA deficiency, or DEF6 deficiency." (PMID 33996698, 2021). "Both genetic mouse models and recent evidence obtained from patients show a critical role for Def6 in autoimmunity." (PMID 33373293, 2020). "A large body of work has also established the immunoregulatory function of Def6 in innate and adaptive immunity as well as in autoimmunity." (PMID 33373293, 2020). "Def6 is a new systemic lupus erythematosus (SLE) risk variant and recent evidence obtained from patients show a critical role for Def6 in autoimmunity." (PMID 33373293, 2020). "The role of DEF6 in murine autoimmunity models has been controversial as the development of autoimmunity appears to depend on their genetic background." (PMID 31308374, 2019). "Our discovery of a mechanistic link between DEF6 mutations and CTLA-4 functional integrity offers insights to autoimmunity in humans." (PMID 31308374, 2019). "Here the authors identify homozygous DEF6 mutations in patients with severe autoimmunity, one of which received and responds to CTLA-4-Ig, and show that DEF6 is crucial for CTLA-4 cell surface trafficking and immune regulatory function." (PMID 31308374, 2019). "Individuals with the risk C allele were associated with decreased expression of DEF6 which might fail to regulate CTLA-4 availability and trafficking leading to overactivation of autoimmunity." (PMID 32566688, 2020). "Interestingly, other studies of Def6-knockout mice contrarily revealed resistance to uveitis and experimental autoimmune encephalitis, and to date it remains unclear whether susceptibility to autoimmunity is dependent on the genetic background of the mice or other factors." (PMID 31308374, 2019). "However, DEF6 not only affects Th1 and Th2 responses but also plays a role in murine Th17-mediated autoimmunity." (PMID 28993769, 2017). "Our data, thus, supports the notion that SLAT/Def6 may be a promising drug target for T cell-mediated autoimmunity and inflammation." (PMID 22815639, 2012). "Thus, the role of DEF6 in autoimmunity has remained controversial and partially enigmatic." (PMID 31308374, 2019). "In conclusion, our work identifies a role for DEF6 in regulating CTLA-4 availability and trafficking to prevent autoimmunity, in line with CTLA-4 functioning both as immune rheostat and defining thresholds of immune activation for anti-cancer immunity." (PMID 31308374, 2019).
lupus (8 papers, 2017 to 2025). "Of note, DEF-6 is a genetic risk variant for human lupus, a fact indicating that SWEF is involved in SLE pathogenesis in humans, as well." (PMID 39918986, 2025). "Subsequently, it was demonstrated that global heterozygous deficiency of IRF5 also reduces disease in the Lyn-deficient mouse lupus model, the gld.apoE-deficient mouse lupus model, and in the Swap70-deficient Def6-deficient mouse lupus model." (PMID 34197340, 2021). "On the other hand, it has been described that mice deficient in both SWAP-70 and its homolog DEF6 develop systemic lupus erythematosus, indicating that DEF6 expression might at least partially compensate for defects in Swap-70-/- mice." (PMID 35359955, 2022). "IL-21 was found to be crucial for ABC development in the SWAP-70 and DEF6 double knock-out (DKO) model of lupus as well as the E.muris infection model." (PMID 36072594, 2022). "Irf5 has also been reported to be required for ABC formation in the SWAP-70 and DEF6 double knock-out lupus model." (PMID 36072594, 2022). "Knockout of Swap-70 and Def6 (double-knockout, DKO) led to the spontaneous expansion of ABCs and development of lupus in C57BL/6 mice." (PMID 31795353, 2019). "Notably, double knockout (DKO) of Def6 and SWAP70 in C57BL/6 mice results in development of lupus, predominantly in female mice as in human SLE21." (PMID 28811467, 2017).
autoimmune disease (7 papers, 2012 to 2025). A disorder resulting from loss of function or tissue destruction of an organ or multiple organs, arising from humoral or cellular immune responses of the individual to their own tissue constituents. "Many studies involving mice and humans have demonstrated that DEF6 deficiency is closely correlated with autoimmune diseases." (PMID 37524688, 2023). "DEF6 is a gene associated with human immunity, and its deficiency is closely related to autoimmune diseases." (PMID 36686789, 2022). "Recent human genetic evidence, together with results obtained from animal models and patients, reveal the important regulatory role for Def6 in immunity and autoimmune diseases, such as SLE and RA." (PMID 33373293, 2020). "In non-cancerous disease, DEF6 deficiency can lead to reduced numbers of T and B cells, autoimmune diseases, hepatosplenomegaly, and bowel inflammation." (PMID 36686789, 2022). "Although aberrant expression may occur in tumor settings, the almost exclusive expression of DEF6 in T cells renders DEF6 as an especially interesting selective target for T cell-mediated inflammatory and autoimmune diseases." (PMID 28993769, 2017).
lupus-like syndrome (5 papers, 2015 to 2021). "Def6 deficient female mice on a mixed 129/BL6 background develop a lupus-like syndrome." (PMID 33373293, 2020). "Here we have employed mice that lack the expression of DEF6 and SWAP-70, two molecules known to restrain IRF4 function in T and B cells, to explore the contribution of DC-IRF4 to the lupus-like syndrome that develops in these mice." (PMID 26544714, 2015). "Absence of DEF6 and SWAP-70, two homologous guanine exchange factors, in double-knock-out (DKO) mice leads to a lupus-like syndrome in females marked by accumulation of ABCs." (PMID 34376664, 2021). "Notably, the concomitant lack of DEF6 and Swap-70 in C57BL/6 mice spontaneously develop a lupus-like syndrome in aging female mice." (PMID 33274247, 2020).
ovarian carcinoma (3 papers, 2016 to 2022). A malignant neoplasm originating from the surface ovarian epithelium. "Ovarian carcinoma patients with high DEF6 expression were associated with a poor overall survival compared with the patients with low DEF6 expression (P = 0.008)." (PMID 27488395, 2016). "Ovarian carcinomas positive for both DEF6 and p16 expression were associated with the worst OS (P = 0.027) and DFS (P = 0.023), whereas those negative for both DEF6 and p16 had the best OS and DFS." (PMID 27488395, 2016). "In clear cell renal cell carcinoma, a high level of expression of DEF6 predicts poor prognosis; in human osteosarcoma, a high level of expression of DEF6 is associated with metastasis and poor prognosis; in ovarian carcinoma, a high level of expression of DEF6 is associated with poor prognosis." (PMID 36686789, 2022). "In this study of 180 cases of ovarian carcinoma using immunohistochemistry, a high expression of DEF6 was commonly found in ovarian carcinomas, and associated with different histology subtypes, advanced FIGO stage, and reduced overall survival (OS) and disease free survival (DFS)." (PMID 27488395, 2016). "Among six ovarian carcinoma cells examined, the expression of DEF6 in TOV-112D (endometrioid carcinoma) and OVCAR3 (serous carcinoma) cells were found to be relatively high when compared to other ovarian cells." (PMID 27488395, 2016). "DEF6 was often overexpressed in ovarian carcinomas, particularly in high-grade serous carcinoma and endometrioid carcinoma cells and tissues." (PMID 27488395, 2016). "Hence DEF6 expression deserves further investigation especially its potential as therapeutic target in the dreadful ovarian carcinomas." (PMID 27488395, 2016). "The expression profile of DEF6 was studied in several ovarian carcinoma cell lines by Western blot." (PMID 27488395, 2016).
autoimmune hemolytic anemia (2 papers, 2019 to 2020). Autoimmune hemolytic anemia (AIHA) is an autoimmune disorder in which various types of auto-antibodies are directed against red blood cells causing their survival to be shortened and resulting in hemolytic anemia. "Clinical and immunological phenotypes in DEF6-mutated patients include T-cell lymphopenia, low class-switched B cells, hepatosplenomegaly, autoimmune hemolytic anemia and bowel inflammation, all of which are reminiscent of CTLA-4 haploinsufficiency and LRBA deficiency." (PMID 31308374, 2019). "Patients with DEF6-mutation presented with CTLA-4 haploinsufficiency and LRBA deficiency including T cell lymphopenia, low class-switched B cells, hepatosplenomegaly, autoimmune hemolytic anemia, and bowel inflammation." (PMID 32566688, 2020).
colorectal cancer (2 papers, 2016 to 2022). A primary or metastatic malignant neoplasm that affects the colon or rectum. "DEF6 not only is abnormally expressed in colorectal cancer but is also closely related to prognosis." (PMID 36686789, 2022). "DEF6 was expressed in breast cancer cells, oral squamous cell carcinoma, colorectal carcinoma, and in tumor vessels of renal cell carcinoma." (PMID 27488395, 2016). "We performed an IHC analysis to verify the relationship between DEF6 and colorectal cancer." (PMID 36686789, 2022). "In colorectal cancer, immunohistochemistry for DEF6 can be used for lymph node staging and may be adopted in clinicopathological diagnosis after more in-depth validation." (PMID 36686789, 2022).
experimental autoimmune encephalomyelitis (2 papers, 2012 to 2017). An autoimmune demyelinating disease of the central nervous system that is produced experimentally in animals by the injection of homogenized brain or spinal cord in Freund's adjuvant. "Recently, SLAT/Def6 has been shown to play a major role in the development and pathogenesis of Th17 cell-mediated experimental autoimmune encephalomyelitis (EAE)." (PMID 22815639, 2012).
Immunodeficiency (2 papers, 2019 to 2021). Failure of the immune system to protect the body adequately from infection, due to the absence or insufficiency of some component process or substance. "While patients with germline mutations in CTLA-4, LRBA and DEF6 commonly display features such as immune dysregulation and immune deficiency, mice with similar genetic defects are relatively healthy, even upon infectious challenging or aging." (PMID 33996698, 2021).
asthma (1 paper, 2024). "Specifically, three genes were associated with increased asthma risk in the lung and a decreased risk for asthma in the blood (i.e., RERE, UNC13D, and OIP5-AS1), and two genes (i.e., RP5-1115A15.1 and DEF6) had the opposite effect." (PMID 39628479, 2024).
autoimmune uveitis (1 paper, 2012). An autoimmune form of uveitis (disease). "Here, we investigated the role of SLAT/Def6 in the development of experimental autoimmune uveitis (EAU), an animal model for several uveitic conditions in humans." (PMID 22815639, 2012).
breast carcinoma (1 paper, 2016). "Increased expression of DEF6 has been shown to be correlated with the malignant behavior of extra-skeletal myxoid chondrosarcoma, colorectal cancer, breast cancer cells, and oral squamous cell carcinoma." (PMID 27488395, 2016).